MIR4291 (microRNA 4291)
Synonyms: hsa-mir-4291
Gene: MicroRNA gene on chromosome 9 (93,819,357 to 93,819,421, forward strand). Ensembl gene ENSG00000265347.
Homologues: Orthologues: chimpanzee MIR4291 (100% identical).